DANCR (differentiation antagonizing non-protein coding RNA)
Diseases named in the same sentence as DANCR in open-access papers (continued):
Sharing a sentence is not in itself a finding about the gene and the disease.
cancer (continued). "DANCR abnormal expression in various human cancers has been shown to play active roles through regulating cancer-related phenotypes, as promoting cell proliferation, migration, invasion, inhibiting apoptosis." (PMID 33123287, 2020). "DANCR is an lncRNA acting as an oncogene in various types of cancer including esophageal squamous cell carcinoma, cervical cancer and hepatocellular carcinoma." (PMID 32159208, 2020). "In these different cancers, DANCR mainly functions as an oncogene via promoting cell proliferation, invasion, migration, and/or inhibiting cell apoptosis." (PMID 32123519, 2020). "Next, we evaluated the role of DANCR in PC cell migration and invasion, which are critical factors in cancer progression and metastasis." (PMID 31515968, 2020). "This review summarizes the current studies of functions and regulation mechanisms of DANCR in human cancers." (PMID 33123287, 2020). "Conclusively, DANCR is a considerable promoter of cancers with a bright prospect in targeted therapy." (PMID 31799189, 2019). "Herein, we review some common targets of DANCR which are discovered to interact with DANCR in multiple cancers and further discuss the role of DANCR in particular cancers to better understand the regulatory mechanism of DANCR." (PMID 31799189, 2019). "In this section, the role of DANCR in particular cancers is discussed so as to clarify the molecular mechanisms of DANCR in a more specific way and instruct the therapy of DANCR aberrantly-expressed cancers." (PMID 31799189, 2019). "DANCR is also a critical oncogenic regulator which presents an increasingly important status in cancer study." (PMID 31799189, 2019). "In the wake of the deepening of the research, DANCR was found to be aberrantly expressed in numerous cancers and exerted multiple regulating functions." (PMID 31799189, 2019). "Extensive data have shown that DANCR correlates with the prognosis of various human cancers, and exerts diverse oncogenic functions via multiple downstream targets." (PMID 31799189, 2019). "When DANCR was knocked down, cancer cell proliferation, migration and invasion were inhibited, and cell apoptosis was increased." (PMID 29266795, 2018). "The down‐regulation of DANCR attenuated cancer cell proliferation, migration and invasion and facilitated cancer cell apoptosis." (PMID 29266795, 2018). "Our findings have shed light into a novel roles of DANCR in TNBC tumorigenesis which have significant implications on better understanding the function of DANCR in human cancers." (PMID 30518934, 2018). "In recent years, many studies have been conducted to evaluate the function of DANCR in biological processes, including stem cell differentiation, cell proliferation and cancer progression." (PMID 29266795, 2018). "We found that the expression level of DANCR is up‐regulated in cancer tissues compared with that in adjacent normal tissues." (PMID 29266795, 2018). "DANCR has been reported as an oncogene in various carcinomas." (PMID 41602364, 2026). "This indicates that DANCR may act within key proliferation inducing gene regulatory networks as a pan-cancer oncogene." (PMID 41336739, 2025). "Our work suggests that cancer-critical lncRNAs such as DANCR, expressed from similar regions in vertebrate genomes, may control related genes and processes involved in both embryonic development and tumorigenesis across species." (PMID 41336739, 2025). "Our results do not discriminate between these scenarios and indicate that human and zebrafish DANCR may function as regulators of genes involved in shared biological processes and pathways crucial for development and dysregulated in cancer." (PMID 41336739, 2025). "Our findings suggest that positionally equivalent lncRNAs such as DANCR may perform related roles in development and cancer across different species." (PMID 41336739, 2025). "Human DANCR is a growth promoting oncogene in several different cancers." (PMID 41336739, 2025).
cancer (continued). "In addition, miR-29b-1/a, lidocaine and bupivacaine were shown to downregulate DANCR expression, inhibiting cancer cell progression." (PMID 38877534, 2024). "Furthermore, E2F1 also activated DANCR transcription, forming an E2F1/DANCR/miR-34c-5p positive feedback loop, presenting novel approaches for tackling cancer progression." (PMID 39119602, 2024). "The high clonogenic activity of HAN-1 cells can be related to increased expression of several long non-coding RNAs, such as TUG1, MEG3, MALAT1, NEAT1, and DANCR – all considered as modulators of stemness of cancer cells, their differentiation potential and chemoresistance." (PMID 38342891, 2024). "Consequently, this study identified DANCR as a novel effector molecule in the downstream pathway of doxorubicin, addressing doxorubicin resistance across different cancer types." (PMID 38877534, 2024). "Despite the identified role of DANCR in mediating drug resistance in multiple cancer types, investigations into its precise contribution to this phenomenon remain in nascent stages, and the underlying mechanisms remain unclear." (PMID 38877534, 2024). "Up-regulation of DANCR has been reported in many types of cancers." (PMID 35590326, 2022). "Moreover, DANCR participates in the progression of this type of cancer through sequestering miR‐496 and further modulating expression of mTOR." (PMID 35590326, 2022). "In addition, lncRNA SNHG6, LINC00520, PCAT6, KCNMB2-AS1, and DANCR, serving as ceRNAs, have been reported to be regulated in multiple cancers." (PMID 35909518, 2022). "DANCR is regarded as an oncogene in almost all types of cancers." (PMID 35590326, 2022). "It has been verified that DANCR is aberrantly expressed in many cancers." (PMID 34722539, 2021). "In addition, DANCR was reported to overexpress in multiple types of cancers, implicating its important function in tumorigenesis." (PMID 33414433, 2021). "According to previous studies, lncRNA DANCR functioned as an oncogene in several cancers." (PMID 35096816, 2021). "Besides, lncRNA DANCR expression in cancer tissues was evaluated using quantitative reverse transcription polymerase chain reaction (qRT-PCR) in all studies." (PMID 30910838, 2021). "Hopefully, this data added DANCR as a new effector in the downstream pathway of Dox, which may help resolve the problem of drug resistance to Dox in multiple cancer types." (PMID 33414433, 2021). "Not only in cancer, DANCR could also participate in various biological processes and other diseases." (PMID 34722539, 2021). "These encouraging researches indicate that circulating DANCR may be a novel non−invasive biomarker for cancer diagnosis." (PMID 34722539, 2021). "Overall, high lncRNA DANCR expression was an unfavorable factor in the cancer prognosis." (PMID 30910838, 2021). "Based on these studies, DANCR is emerging as an oncogenic lncRNA in cancers." (PMID 33414433, 2021). "The downstream regulatory mechanisms for the biological roles of DANCR in cancers are complicated." (PMID 34722539, 2021). "In addition, DANCR had also been demonstrated to be involved in the proliferation, metastasis, angiogenesis, and differentiation in various cancer types, such as osteosarcoma, glioma, breast cancer, cervical cancer, bladder cancer, etc.25–28,31–33." (PMID 33414433, 2021). "In addition, recent studies have reported that inhibition of DANCR affects cancer cell progression, invasion, and migration in many carcinomas." (PMID 34065991, 2021). "Among the genes positively associated with DANCR, we noted FRAT1 and FRAT2, which are positive regulator of the Wnt/β-catenin signaling pathway and have oncogenic roles in several cancers." (PMID 32123519, 2020). "Several reports showed that DANCR stimulates cancer stem‐cell features." (PMID 31860165, 2020). "They found that the miR-216a level in cancer cells was negatively correlated with DANCR expression." (PMID 33123287, 2020).
cancer (continued). "Several articles have confirmed that DANCR could function as a ceRNA to regulate the expression of specific genes, exerting its oncogenic function in various cancers." (PMID 33123287, 2020). "In addition, a recent meta-analysis and systemic review illustrated that DANCR expression is of significant prognostic value in various cancers." (PMID 31799189, 2019). "To date, researches on targeting DANCR for cancer therapy remains limited." (PMID 31799189, 2019). "As we can see, due to the diverse mechanisms of DANCR and limited research on it, it is hard to foresee the unknown mechanisms and functions of DANCR in cancers." (PMID 31799189, 2019). "Experiments demonstrated that miRNA-216a-5p interacted with DANCR and its inhibitor could weaken the influences induced by DANCR knockdown for cancer cells, including cell proliferation and invasion, and the expression of Nanog, SOX2, and OCT4." (PMID 30910842, 2019). "Herein, we summarize the functions and molecular mechanism of DANCR in human cancers." (PMID 31799189, 2019). "DANCR is a typical oncogenic lncRNA which exerts multiple functions in cancer development." (PMID 31799189, 2019). "The massive targets of miR-216a complicate the functions of DANCR in cancer cells." (PMID 31799189, 2019). "DANCR is located in human chromosome 4q12, and is reported as an oncogene in diverse carcinomas." (PMID 29753317, 2018). "It generates miR-4449 and SNORA26 and is downregulated during differentiation, hence upregulated DANCR might contribute to cancer by maintaining a pro-proliferative state." (PMID 25587025, 2014). "Besides BC, the role of lncRNA DANCR was also reported in different types of cancer." (PMID 35150011, 2022). "If TFSs are used as anchors by TAD-lncRNAs such as DANCR to mediate chromatin organization, their deregulation can disrupt the formation of TFSs and may alter chromatin organization contributing to diseases including cancer." (PMID 34049493, 2021). "In the present study, we identified DANCR from GSE126092 microarray dataset including differential lncRNA/mRNAs between CRC and normal tissue samples, knowing that dysregulation of DANCR may affect the proliferation, differentiation and apoptosis of many types of cancer cells, including CRC." (PMID 32159208, 2020). "Importantly, several studies indicated that DANCR could play a critical roles in the EMT and migration of cancer cells and suggested that DANCR participates in the initiation and progression of IPF." (PMID 32010478, 2020). "However, the mechanisms underpinning the functions of DANCR in different cancers are various." (PMID 32123519, 2020). "Moreover, DANCR can manipulate more than one target in cancer and join in multiple pathways." (PMID 31799189, 2019). "In addition, recent researches have also proved that DANCR exerts oncogenic functions in many cancers, for example, it could promote cell proliferation and invasion by miR-758-3p." (PMID 30910842, 2019). "Immunohistochemical staining revealed that Ki67 level was obviously lower in cells transfected with LV-sh-DANCR than those transfected with LV-sh-control, which suggested that down-regulation DANCR could also reduce cancer cell proliferation and migration in vivo." (PMID 30910842, 2019). "Therefore, DANCR may perform different function and expression in different cancer types and cancer cell lines." (PMID 30910839, 2019). "Upregulation of DANCR and SOX2OT in PTC was observed to correlate with cancer onset, and cancer onset and progression, respectively." (PMID 38785786, 2024). "It has been reported that miR-1-3p can be silenced by several lncRNAs such as MALAT1, DANCR, and RMRP in cancers." (PMID 39061232, 2024). "Intriguingly, the DANCR lncRNA is activated by the KLF5 master regulator in GC, known to undergo genomic amplification in this form of cancer." (PMID 39456519, 2024). "Overexpression of DANCR stimulated epithelial‐mesenchymal transition (EMT), cancer stemness, inflammation, and vice versa." (PMID 35150011, 2022).
cancer (continued). "This is in line with previous studies in other malignancies, whereby the impairment of miR-214-5p by competitor endogen RNAs (e.g. DANCR, LINC00963 and circ-XPR1) promotes cancer cell proliferation and metastasis." (PMID 34113568, 2021). "A large number of recent studies have focused on exploring the role of m6A-methylated mRNA in cancer cells, and some LncRNAs such as LINC00958, DANCR, and MALAT1 modified by m6A have also been reported." (PMID 34544449, 2021). "In summary, we identified lncRNA DANCR as the master regulator of inflammation as well as inflammation‐mediated EMT and cancer stemness." (PMID 31860165, 2020). "Various lncRNAs (including DANCR, SCAT7 and AK023391) have been reported to stimulate the PI3K/AKT pathway in cancers." (PMID 31808752, 2019). "We then tested the effects of DANCR knockdown on the process of epithelial-mesenchymal transition (EMT), a critical step for cancer metastasis." (PMID 29416741, 2018). "Then, the expression levels of DANCR were evaluated in three ADC cell lines (A549, H1299 and H358) and the HBE cell line; DANCR expression was significantly increased in all three cancer cell lines." (PMID 29266795, 2018). "In the present study, we used qRT-PCR to quantify the expression levels of DANCR in 63 pairs of TNBC subtype tissues, and we found that lncRNA DANCR expression increased in TNBC cancer tissues and TNBC cell lines." (PMID 28760736, 2017). "DANCR levels correlate with essential growth regulatory genes including c-MYC across CCLE cancer cell lines and it is highly expressed in many different types of cancer." (PMID 41336739, 2025). "The interplay between DANCR and EZH2 plays a pivotal role in regulating cancer progression." (PMID 38877534, 2024). "However, our results suggest that lncRNA DANCR is a novel target for IGF2BP2 through m6A modification in PC, and that it promotes cancer stemness-like properties and PC pathogenesis." (PMID 32754191, 2020). "In agreement with previous reports on various types of human cancers, DANCR may also act as an oncogene in ESCC progression, supporting that DANCR may offer a potential therapeutic target for those ESCC patients harboring mutations of ZNF750." (PMID 32341351, 2020). "For example, DANCR, which was also up-regulated in young vaccine responders at day 7, as discussed in a previous publication, was found to influence the activity of Enhancer of Zeste Homolog 2 (EZH2) in multiple cancer types." (PMID 31399544, 2019). "Among the eight validated lncRNAs, there are three with relevance to cancer, MIR17HG, USP2-AS1, and DANCR; the roles of the remaining five are currently not known." (PMID 25587025, 2014).
infection (3 papers, 2020 to 2023). The state of being infected such as from the introduction of a foreign agent such as serum, vaccine, antigenic substance or organism. "The data of bioinformatics clearly showed that DANCR was closely related to the infection process dominated by pathogen invasion." (PMID 37125193, 2023). "We found in the qRT-PCR analysis that CTNNB1 mRNA expression was significantly inhibited by miR-320a mimics and promoted by miR-320a inhibitor, while DANCR expression remained unchanged upon infection." (PMID 32778797, 2020). "Based on these findings, we presume that DANCR might be a crucial node in mediating pathogen infection and autophagy regulation." (PMID 37125193, 2023). "Supporting links of post-infection inflammatory and cognitive damages with cholinergic mal-functioning, man and woman-originated cultured cholinergic neurons presented differentiation-related increases of DANCR and NEAT1 targeting microRNAs." (PMID 33163005, 2020). "To reach this goal, we examined a dataset of DANCR knockdown (KD) in neuron progenitor cells and found downregulation of cytokines and the non-canonical pathway NFkB (IL-6 and NFKB2, p<0.05, FDR), indicating increased susceptibility to infection in differentiated neurons." (PMID 33163005, 2020). "Furthermore, DANCR has been shown to affect HIF1a’s stability in malignancy, suggesting that the mechanism controlling this interaction may likewise be operational in other contexts, including infection control." (PMID 33163005, 2020). "Thus, the changes in DANCR and NEAT1 may lead to the infection-related impact of those miRs and regulate the inflammation signature associated with them in epithelial cells, albeit in a sex-related manner." (PMID 33163005, 2020).
DANCR also shares sentences with these, for which no sentence is quoted: prostate tumor (3 papers); cardiac hypertrophy (2); heart failure (2); adenocarcinoma (1); ankylosing spondylitis (1); asthma (1); cardiovascular diseases (1); diabetes mellitus (1); esophageal cancer (1); gall bladder cancer (1); hematological disorders (1); kidney (1); large cell carcinoma (1); metastasis (1); metastatic melanoma (1); pituitary tumor (1); prostate adenocarcinoma (1); sarcopenia (1); squamous cell carcinoma (1); stomach cancer (1); urothelial bladder cancer (1); uveal melanoma (1).